RN7SL162P (RNA, 7SL, cytoplasmic 162, pseudogene)
Gene: Miscellaneous RNA gene on chromosome 22 (28,642,979 to 28,643,270, reverse strand). Ensembl gene ENSG00000266503.
Homologues: Orthologues: chimpanzee Metazoa_SRP (98% identical), macaque Metazoa_SRP (94% identical), dog Metazoa_SRP (56% identical). Paralogues in human: RN7SL1 (85% identical), RN7SL2 (84% identical), RN7SL3 (83% identical), RN7SL126P (83% identical), RN7SL45P (81% identical), RN7SL664P (81% identical), RN7SL679P (80% identical), RN7SL88P (80% identical), RN7SL336P (80% identical), RN7SL451P (80% identical), RN7SL615P (80% identical), RN7SL743P (80% identical), and 701 more.